DOK6 (docking protein 6)
Description:
DOK proteins are enzymatically inert adaptor or scaffolding proteins. They provide a docking platform for the assembly of multimolecular signaling complexes. DOK6 promotes Ret-mediated neurite growth. May have a role in brain development and/or maintenance.
Synonyms: DOK5L; MGC20785; HsT3226
Tractability: No criterion of Open Targets' tractability assessment is met for any kind of drug.
Gene: Protein-coding gene on chromosome 18 (69,400,888 to 69,849,087, forward strand). Ensembl gene ENSG00000206052.
Subcellular location (Human Protein Atlas): Cytosol; Focal adhesion sites
Pathways (Reactome):
Developmental Biology: RET signaling
Gene Ontology:
Molecular function: protein binding; signaling adaptor activity
Cellular component: cytosol
Genetic constraint (gnomAD): Loss-of-function variants: 19 observed, 40.29 expected, observed/expected ratio (o/e) 0.47, 90% interval 0.33 to 0.69. The upper end of that interval is the gene's LOEUF score, 0.69, which puts it in group 2 of 6, group 1 being the genes least tolerant of losing a copy. Missense variants: 319 observed, 399.1 expected, observed/expected ratio (o/e) 0.8, 90% interval 0.73 to 0.88. Synonymous variants: 152 observed, 141.81 expected, observed/expected ratio (o/e) 1.07, 90% interval 0.94 to 1.23.
Homologues: Orthologues: chimpanzee DOK6 (100% identical), mouse Dok6 (99% identical), rat Dok6 (99% identical), dog DOK6 (99% identical), guinea pig DOK6 (99% identical), rabbit DOK6 (98% identical), pig DOK6 (98% identical), macaque DOK6 (88% identical), tropical clawed frog DOK6 (84% identical), zebrafish dok6 (81% identical), Caenorhabditis elegans rog-1 (18% identical), Drosophila melanogaster Dok (18% identical), and 1 more. Paralogues in human: DOK5 (65% identical), DOK4 (62% identical), DOK1 (23% identical), DOK2 (21% identical), DOK3 (20% identical), FRS3 (14% identical), FRS2 (13% identical).
Diseases named in the same sentence as DOK6 in open-access papers:
DOK6 is named in the same sentence as 25 diseases in open-access papers, as found by Europe PMC text mining. Sharing a sentence is not in itself a finding about the gene and the disease. The quoted sentences say what the papers report.
breast carcinoma (3 papers, 2018 to 2021). "Recently, several studies of other DOK proteins such as DOK1, DOK2, and DOK6 participate in the occurrence and development of breast cancer." (PMID 33552156, 2021). "Recent studies also demonstrated the potential role of DOK6 in solid tumors such as gastric cancer and breast cancer." (PMID 31486300, 2019). "In prostate, stomach, and breast cancer, DOK6 and MOB3B were reported as putative tumor suppressor genes." (PMID 30454026, 2018).
gastric cancer (2 papers, 2017 to 2019). A primary or metastatic malignant neoplasm involving the stomach. "This marked effect on signaling was consistent with the loss of the phosphotyrosine-binding domain encoded by exon 5 of DOK6 in the lowest quartile gastric cancers." (PMID 29872697, 2017). "Our data suggest that DOK6 expression is an integrated biomarker of multiple oncogenic signals in gastric cancer and identify FRA18C as a new cancer-associated fragile site." (PMID 29872697, 2017). "We compared the expression of 34 genes telomeric to DOK6 for which RPKM values were available between two gastric cancer groups in the TCGA STAD data set." (PMID 29872697, 2017). "Multiple oncogenic signaling pathways (gastrin-CREB, NGF-neurotrophin, PDGF, EGFR, ERK, ERBB4, FGFR1, RAS, VEGFR2 and RAF/MAP kinase) known to be active in aggressive gastric cancers were strikingly diminished in gastric cancers with low DOK6 expression." (PMID 29872697, 2017). "Analysis of genes that were differentially expressed between low and high DOK6-expressing gastric cancers point to a role for DOK6 in concurrently mediating multiple oncogenic signaling pathways." (PMID 29872697, 2017). "A striking majority of differentially expressed genes in low compared to high DOK6-expressing gastric cancers were underexpressed (3797 of 3834 genes; 99%), among which the largest functional group were genes involved in signal transduction." (PMID 29872697, 2017). "The breakpoint mapped to intron 4 of DOK6 within FRA18C in a gastric cancer cell line, which had greatly reduced DOK6 transcription." (PMID 29872697, 2017). "DOK6 expression correlated with several histopathological, molecular and clinical features of gastric cancer tumors." (PMID 29872697, 2017). "Taken together, copy number and transcriptome analysis identified a subset of primary gastric cancers with a chromosomal break at FRA18C characterized by diminished DOK6 expression." (PMID 29872697, 2017). "In a typical gastric cancer harboring this abnormal chromosome, truncation of DOK6 intron 4 was evident with break-apart BAC probes flanking the breakpoint (RP11-22G18; chr18:67,564,184–67,743,728 labeled with SpectrumGreen and RP11-98M3; chr18: 67,198,763–67,355,215 labeled with SpectrumOrange)." (PMID 29872697, 2017). "Gene deletions in common fragile sites have been rarely reported in gastric cancer, neither is DOK6 expression known to have biological associations with gastric cancer." (PMID 29872697, 2017). "Copy number loss at FRA18C was significantly more prevalent but not uniform among gastric cancers in the lowest quartile, indicating that DOK6 expression was reduced in some tumors by mechanisms other than copy number loss." (PMID 29872697, 2017). "By combining chromosome sorting, array painting and high-resolution copy number analysis, we identified recurrent truncation of DOK6 in intron 4 at the FRA18C locus in MKN7 cells and found the same abnormality in 22% of primary gastric cancer tumors by break-apart FISH assay." (PMID 29872697, 2017). "Their combined oncogenic effects could explain the significantly shorter survival of gastric cancer patients with high DOK6 tumors and explain why the level of DOK6 expression alone is prognostic independent of TNM stage, currently the only prognosticator in clinical practice." (PMID 29872697, 2017). "The first group comprised gastric cancers that had low DOK6 expression and FRA18C copy number deletion (n = 24); the second group comprised all other gastric cancers in the same data set without FRA18C deletion and DOK6 expression above the lowest quartile (n = 229)." (PMID 29872697, 2017).
osteoporosis (2 papers, 2011). A condition of reduced bone mass, with decreased cortical thickness and a decrease in the number and size of the trabeculae of cancellous bone (but normal chemical composition), resulting in increased fracture incidence. "DOK6 has been recently found in a GWAS for osteoporosis, although our lead SNP is not in LD with this variant." (PMID 21931561, 2011). "Comparison of our GWAS data with SNPs identified in previous GWASs on osteoporosis showed five SNPs in three genes (PLCL1, DOK6, and MEF2C) with P values below 0.05." (PMID 21573128, 2011).
acute myeloid leukemia (1 paper, 2019). Acute myeloid leukemia (AML) is a group of neoplasms arising from precursor cells committed to the myeloid cell-line differentiation. "Herein, we verified the promoter methylation status of DOK6 and further explored its clinical implication in de novo acute myeloid leukemia (AML)." (PMID 31486300, 2019).
leukemia (1 paper, 2019). A malignant (clonal) hematologic disorder, involving hematopoietic stem cells and characterized by the presence of primitive or atypical myeloid or lymphoid cells in the bone marrow and the blood. "Furthermore, the cell experiment indicated that 5‐aza‐dC increased DOK6 expression in leukemia cells THP‐1 by inducing demethylation of the DOK6 promoter region." (PMID 31486300, 2019).
myeloid malignancies (1 paper, 2019). "However, previous studies of DOK6 have not dealt with its roles in myeloid malignancies." (PMID 31486300, 2019).
neuropathy (1 paper, 2024). A disorder affecting the nervous system that manifests with pain, tingling, numbness, and/or muscle weakness. "In Dok6-lacking mice, there was a significant abnormal myelination phenotype, including: (a) inhibition of radial sorting and delay of the sciatic nerve myelination at an early stage; and (b) developing neuropathy-like focal myelin abnormalities." (PMID 38351062, 2024).
pancreatitis (1 paper, 2025). Inflammation of the pancreas. "Differential expression of DOK6 was predicted in patients with severe pain in pancreatitis with greatest effect in nerve tissue." (PMID 39674387, 2025).
stomach adenocarcinoma (1 paper, 2017). "Analysis of The Cancer Genome Atlas stomach adenocarcinoma cohort showed significant correlation of DOK6 expression with histological and molecular phenotypes." (PMID 29872697, 2017).
tumor (3 papers, 2013 to 2021). "Univariate analysis identified a significant correlation between SSTR2 and the response to the acute SA test, while SA treatment, RORC and DOK6 mRNA levels were correlated with tumor size." (PMID 23825587, 2013).
peripheral neuropathy (1 paper, 2024). A disorder affecting the peripheral nervous system. "In this study, we identified DOK6 as a novel factor involved in the maintenance of peripheral axons, and found that loss of Dok6 leads to typical symptoms of peripheral neuropathy in mice." (PMID 38351062, 2024). "Genetic deletion of Dok6 results in typical peripheral neuropathy symptoms such as abnormal posture and aberrant gait, nociceptive hyposensitivity, severe paw injury and deformity, peripheral myelin abnormalities, and decreased of nerve conduction velocities." (PMID 38351062, 2024). "In summary, Dok6 deletion in mice results in a typical peripheral neuropathy, including decreased nociceptive and proprioceptive sensitivity, reduced nerve conduction velocities and abnormal peripheral myelination." (PMID 38351062, 2024).
renal disease (1 paper, 2011). "Although a direct role in renal disease has not been described so far, DOK6 interacts with Ret, the ablation of which resulted in kidney agenesis in model systems." (PMID 21931561, 2011).
DOK6 also shares sentences with these, for which no sentence is quoted: Hirschsprung disease (2 papers); Alzheimer disease (1); Anxiety (1); cancer (1); Charcot-Marie-Tooth disease (1); colorectal cancer (1); depression (1); diabetes (1); epilepsy (1); multiple endocrine neoplasia type 2A (1); Obesity (1); prostate carcinoma (1); schizophrenia (1).